CLDN7 (claudin 7)
Diseases named in the same sentence as CLDN7 in open-access papers (continued):
Sharing a sentence is not in itself a finding about the gene and the disease.
ovarian carcinoma (30 papers, 2008 to 2025). A malignant neoplasm originating from the surface ovarian epithelium. "Amyloid precursor-like protein 2 (APLP2) was found directly associated with CLDN7 in ovarian cancer cell line OVCA420." (PMID 32257370, 2020). "High claudin-7 expression has been associated with a poor response to platinum-based chemotherapy in epithelial ovarian cancer." (PMID 23685873, 2013). "Previous studies have shown that claudin-7 is up-regulated in endometriosis associated endometrioid ovarian cancer and also frequently upregulated in other epithelial ovarian cancers along with claudins-3 and -4." (PMID 23685873, 2013). "We performed microarray analysis to identify changes in gene expression associated with CLDN7 knockdown in ovarian cancer." (PMID 21789222, 2011). "Similarly, high CLDN7 expression has been associated with shorter progression-free survival and poor sensitivity to platinum-based chemotherapy in patients with ovarian carcinoma." (PMID 37041570, 2023). "It is worth emphasizing that high expression of claudin-7 in ovarian carcinoma cells causes reduced response to first-line platinum-based combination chemotherapy, and silencing of its expression leads to increased sensitivity to cisplatin, confirming its involvement in the response to chemotherapy." (PMID 32197343, 2020). "Claudin 7 is frequently overexpressed in ovarian cancer and has been linked to increased migration." (PMID 26964739, 2016). "Ginger inhibits ovarian cancer cells’ SKOV3 invasion by regulating m6A methylation through CLDN7, CLDN11, and CD274." (PMID 38575994, 2024). "It’s shown that CLDN is closely associated with most cancers of epithelial origin, especially when CLDN7 promotes cancer cell metastasis, such as in gastric, cervical, and ovarian cancers." (PMID 39175074, 2024). "Patrice J. Morin’s research also indicated that the overexpression of CLDN7 in ovarian cancer can promote tumor invasiveness." (PMID 38124743, 2023). "based on 181 tumor-related tissues suggested that high expression of CLDN7 was associated with poor progression and an independent predictor of survival, suggesting the value of CLDN7 as a prognostic factor in ovarian cancer." (PMID 38124743, 2023). "Some studies showed inverse results, indicating that the overexpression of CLDN7 increased proliferation and migration in gastric adenocarcinoma and promoted invasion in ovarian cancer." (PMID 31998788, 2020). "Among different interacting partners, APLP2 was particularly interesting as our previous report demonstrated that the changes in expression of APLP2 mRNA in CLDN7 siRNA transfected ovarian cancer cell line." (PMID 32257370, 2020). "In our previous study, we demonstrated that CLDN7 is increased in ovarian cancer cell lines and tissues at both mRNA and protein levels." (PMID 32257370, 2020). "CLDN7 is a tight junction protein and increased expression of CLDN7 has been reported in several cancers, including ovarian cancer." (PMID 32257370, 2020). "In our previous study, we highlighted that upregulation of CLDN7 was associated with increased invasion of cancer cells, suggesting a physiological role of CLDN7 in ovarian carcinoma." (PMID 32257370, 2020). "Ovarian cancer showing higher expression of CLDN7 demonstrated lower sensitivity to platinum-based drugs, with increased sensitivity after knockdown of CLDN7, suggesting a direct role of CLDN7 in inducing drug resistance in ovarian cancer cells." (PMID 32257370, 2020). "In ovarian cancer, downregulation of claudin-3/-4 promotes tumor growth and metastasis, while less expression of claudin-3/-4 along with claudin-7 results in high malignancy in breast cancer." (PMID 30728783, 2018). "It was also revealed that CLDN7 is frequently overexpressed and promotes invasion in ovarian cancer." (PMID 30219077, 2018).
ovarian carcinoma (continued). "The levels of CLDN3 and CLDN4 were frequently elevated in pancreatic adenocarcinoma, ovarian cancer, endometrioid adenocarcinoma, and prostate cancer, while CLDN7 has been found to be decreased in invasive ductal carcinomas of the breast." (PMID 28867761, 2017). "Consistent with our data, CLDN3, CLDN4, and CLDN7 have been shown to suppress EMT in ovarian carcinoma cells and lung cancer cells." (PMID 28867761, 2017). "In a previous study, CLDN7 was demonstrated to be significantly differentially expressed in ovarian carcinoma, based on CLDN7 expression analysis at the mRNA and protein levels in 110 patients with epithelial ovarian carcinoma." (PMID 25351113, 2015). "Claudin-7 was found to be universal upregulated in the most common epithelial ovarian cancer subtypes (serous, clear-cell, endometrioid and mucinous) at both the mRNA and protein levels." (PMID 23685873, 2013). "The gene for claudin-7 was found to be upregulated in all tumor samples studied and small-interfering RNA-mediated knockdown of claudin-7 in ovarian cancer cells led to significant changes in the expression of other genes as determined by microarrays." (PMID 23685873, 2013). "The prognostic significance of claudin-7 overexpression in epithelial ovarian cancer patients including sensitivity to platinum-based chemotherapy was investigated in another study." (PMID 23685873, 2013). "In line with these clinical observations, claudin-7 knockdown was shown to increase the sensitivity of ovarian cancer cells to cisplatin treatment in this study." (PMID 24009024, 2013). "With the use of immunobloting and qRT-PCR, the authors demonstrated that mRNA levels and protein levels were not always correlated, suggesting post-translational regulation of claudin-7 in epithelial ovarian cancer." (PMID 23685873, 2013). "Our data show that CLDN7 is elevated at both mRNA and protein levels in most ovarian cancer tissues and cell lines." (PMID 21789222, 2011). "We show that CLDN7 knockdown leads to a decrease in phospho-Erk and an increase in Raf-1 levels, suggesting a possible pathway for claudin-7 signaling in ovarian cancer." (PMID 21789222, 2011). "We find that CLDN7 is elevated in all major subtypes of ovarian cancer: serous, endometrioid, clear cell and mucinous." (PMID 21789222, 2011). "The use of immunoblotting and qRT-PCR allows us to demonstrate that mRNA levels and protein levels are not always correlated, suggesting post-translational regulation of claudin-7 in ovarian cancer." (PMID 21789222, 2011). "In order to investigate claudin-7 protein levels in ovarian cancer, a panel of 29 primary ovarian cancer samples as well as 4 normal ovarian tissues was studied by immunoblotting." (PMID 21789222, 2011). "Between the two ovarian cancer cell lines studied, we identified a total of 1296 genes that were significantly altered following CLDN7 knockdown." (PMID 21789222, 2011). "In order to clearly define the CLDN7 expression patterns in ovarian cancer, microdissected ovarian tumors of various subtypes, as well as cell lines were analyzed by real-time RT-PCR." (PMID 21789222, 2011). "Immunohistochemistry (IHC) experiments confirmed that claudin-7 was expressed at high levels in ovarian cancer." (PMID 21789222, 2011). "CLDN7 mRNA was found to be highly up-regulated in all four major ovarian cancer subtypes (i.e. serous, mucinous, clear cell, and endometrioid) compared with normal ovarian tissues." (PMID 21789222, 2011). "The fact that claudin proteins can be found in the cytoplasm has been reported and in particular, punctate cytoplasmic staining of claudin-7 has been observed in ovarian cancer." (PMID 21789222, 2011). "Small interfering RNA-mediated knockdown of claudin-7 in ovarian cancer cells led to significant changes in gene expression as measured by microarrays and validated by RT-PCR and immunoblotting." (PMID 21789222, 2011).
ovarian carcinoma (continued). "Invasion and migration assays demonstrated clear effects of claudin-7 on the invasive behavior of ovarian cancer cells." (PMID 21789222, 2011). "We first performed transient siRNA-mediated knockdown of CLDN7 expression in two ovarian cancer cell lines (OVCAR-2 and OVCA420) and tested migration using the Oris cell migration assay." (PMID 21789222, 2011). "Using immunofluorescence, claudin-7 staining was found localized predominantly at the cell membrane, with punctate staining in the cytoplasm of ovarian cancer cell lines BG-1, OVCA420 and OVCA433." (PMID 21789222, 2011). "Recent work shows that, in addition to the CLDN3 and CLDN4 genes, CLDN7 is frequently elevated in ovarian cancer." (PMID 21789222, 2011). "In trying to gather additional clues regarding CLDN7 function in ovarian cancer, we investigated gene expression changes following CLDN7 knockdown." (PMID 21789222, 2011). "Because our gene analysis above reveals cell movement as a function possibly affected by CLDN7, we decided to test the possible roles of CLDN7 in ovarian cancer cell migration and invasion." (PMID 21789222, 2011). "To investigate the possible roles of CLDN7 in ovarian cancer, we examined gene expression changes following CLDN7 knockdown." (PMID 21789222, 2011). "Previous studies have shown that claudin-7 is frequently upregulated in epithelial ovarian cancer (EOC) along with claudin-3 and claudin-4." (PMID 21789222, 2011). "Another independent study found claudin-1, claudin-3 and claudin-7 up-regulation together in ovarian cancer effusions predicts poor progression-free and overall survival." (PMID 19440550, 2009). "Previous studies have shown that Claudin-1, Claudin-3, Claudin-4 and Claudin-7 proteins are highly expressed in ovarian carcinoma." (PMID 18781153, 2008). "Additionally, claudin gene regulation differs by tissue: CLDN7 is repressed by the transcription factor Sox9 in colon cancer cells, but in ovarian cancer CLDN7 can be silenced by DNA hypermethylation or post-translational phosphorylation." (PMID 40687428, 2025). "Upregulation of CLDN7 has also been reported in ovarian cancer cell lines, although the evidence is contradictory, given that downregulation of CLDN7 has been observed in human endometriotic lesions and endometrial cancer, promoting proliferation and metastasis." (PMID 38069001, 2023). "However, CLDN3, CLDN4 40, and CLDN7 41 have been shown to suppress EMT in ovarian carcinoma cells and lung cancer cells." (PMID 34405008, 2021). "A few studies observed the claudin-7 overexpression in the ovarian cancer." (PMID 32091301, 2020). "Moreover, they proved that the increased expression of claudin-7 affects the invasion of ovarian cancer cells." (PMID 32197343, 2020). "The aim of the current study was to find interacting partner(s) of CLDN7 in ovarian cancer." (PMID 32257370, 2020). "The goal of this study was to identify proteins interacting with CLDN7 in ovarian cancer." (PMID 32257370, 2020). "They noticed that claudin-7 is upregulated in most of the cases of ovarian cancer." (PMID 32197343, 2020). "Overexpression of CLDN7 has been correlated with poor progression-free survival in ovarian cancer." (PMID 32257370, 2020). "Besides ovarian cancer progression, the complex of EpCAM/claudin-7/CD82 involved in the apoptosis resistance." (PMID 32091301, 2020). "Collectively, our data are consistent with a possible involvement of claudin-7 in ovarian cancer progression and, in the literature, the most recent publications support the pro-metastatic role of a diminished expression of claudin-7 in different type of epithelial cancers." (PMID 32850397, 2020). "This may shed light on the mechanisms and roles of CLDN7 in the development and progression of ovarian cancer." (PMID 32257370, 2020). "In particular, CLDN7 has been shown to be deregulated in ovarian cancer." (PMID 32257370, 2020). "In CRC and ovarian cancer, claudin-7 overexpression promotes tumor formation and invasiveness." (PMID 30728783, 2018).
ovarian carcinoma (continued). "The migration and invasion of ovarian cancer cells is also enhanced by claudin-7 overexpression." (PMID 24009024, 2013). "It is unknown whether these mechanisms are involved in CLDN7 regulation in ovarian cancer, but these possibilities are currently under investigation." (PMID 21789222, 2011). "Using microarrays, we find that many genes are differentially expressed following CLDN7 knockdown and analysis of these genes suggests several pathways through which CLDN7 may function in ovarian cancer." (PMID 21789222, 2011). "CLDN7 may therefore represent potential marker for ovarian cancer detection and a target for therapy." (PMID 21789222, 2011). "For example, claudin-7 is known to be elevated in ovarian cancer as well as other malignancies." (PMID 21789222, 2011). "In summary, we find that CLDN7 is elevated in the vast majority of ovarian cancers." (PMID 21789222, 2011). "In addition, we find that CLDN7 expression is associated with increased invasion, but decreased migration in multiple cell lines providing a functional link to CLDN7 expression in ovarian carcinoma." (PMID 21789222, 2011). "Interestingly, while we found that most claudin-7 staining was localized to the membrane, several ovarian cancer samples exhibited strong cytoplasmic staining." (PMID 21789222, 2011). "However, in ovarian carcinoma, CLDN7 is significantly up-regulated and may be functionally involved in ovarian carcinoma metastasis." (PMID 28055967, 2017). "Overall this work shows that claudin-7 is significantly upregulated in epithelial ovarian cancer and may be functionally involved in ovarian carcinoma invasion, as such claudin-7 may also represent a potential marker for ovarian cancer detection and also a target for therapy." (PMID 23685873, 2013). "However, claudin-7 seems to be up-regulated in gastric cancer and ovarian cancer." (PMID 21310043, 2011). "In summary, ovarian cancer exhibits a pattern of claudin upregulation (CLDN3, CLDN4, CLDN7, CLDN9) that supports tumor growth, dissemination, and chemoresistance." (PMID 40687428, 2025). "The outcomes demonstrated that in ovarian cancer cells SKOV3, CLDN7, CLND11, and CD274 were reduced in the Ginger-treated group than in that of the Con group." (PMID 38575994, 2024). "In line with the sequencing data, our investigation discovered that ginger inhibited the expression of CLDN7, CLDN11, and CD274 in ovarian cancer cells SKOV3." (PMID 38575994, 2024). "In EMT-related genes, Claudin-7 (CLDN7) promotes EMT in colon cancer and ovarian cancer enhanced invasion." (PMID 34445467, 2021). "Eight genes were overexpressed in ovarian cancer samples compared with normal tissue samples and included CLDN1, CLDN3, CLDN4, CLDN6, CLDN7, CLDN9, CLDN10, and CLDN16." (PMID 34249076, 2021). "In summary, this is the first study reporting interaction of CLDN7 with APLP2 and effect of APLP2 on cell survival in the ovarian cancer." (PMID 32257370, 2020). "Like CLDN7, increased levels of APLP2 proteins were found in both ovarian cancer cell lines and ovarian cancer tissue samples." (PMID 32257370, 2020). "As such claudin-7 expression may also represent an independent prognostic factor for PFS and be important in regulating epithelial ovarian cancer response to platinum-based chemotherapy." (PMID 23685873, 2013). "Our work shows that claudin-7 is significantly upregulated in EOC and that it may be functionally involved in ovarian carcinoma invasion." (PMID 21789222, 2011). "Therefore, by altering the m6A methylation levels of CLDN7, CLDN11, and CD274, which in turn affects the multiplication of ovarian cancer cells SKOV3 may be one of the mechanisms by which ginger is anti-SKOV3." (PMID 38575994, 2024). "Therefore, altering the m6A methylation levels of CLDN7, CLDN11, and CD274, which in turn affects the growth of SKOV3 in ovarian cancer cells may be one of the mechanisms by which ginger resists ovarian cancer cells SKOV3." (PMID 38575994, 2024).
ovarian carcinoma (continued). "In this study claudin-7 was found to be expressed in 69/71 (97.1%) epithelial ovarian cancers but not in normal ovaries (p < 0.001) and high claudin-7 expression in primary tumors correlated with shorter progression-free survival (PFS) of patients and poor sensitivity to platinum based chemotherapy." (PMID 23685873, 2013). "Indeed, an early study showed that claudin-7 is overexpressed in all epithelial ovarian cancer subtypes, but is not overexpresssed in sex cord and stromal tumors." (PMID 21789222, 2011).